RHOA (ras homolog family member A)
Diseases named in the same sentence as RHOA in open-access papers (continued):
Sharing a sentence is not in itself a finding about the gene and the disease.
infection (continued). "Among theses studies, a few depicted a positive effect of RhoA or ROCKs on the early stages of infection." (PMID 22952878, 2012). "Reduction in the amount of membrane bound RhoA was found after infection with pYV+ or infection with pYV+ ΔyopT pyopT." (PMID 22792400, 2012). "Here we demonstrate that a Gαq-RhoA pathway is required for both behavioral and immune responses to infection in C. elegans." (PMID 22359503, 2012). "The last example concerns KSHV, which was found to activate RhoA early after infection in human fibroblast cells, with RhoA having a role in the nuclear delivery of viral DNA." (PMID 22952878, 2012). "RhoA phosphorylation was detected in infected cells at 0.5 and 1 h.p.i., thus confirming that the actin bundles observed at early stages of infection are indeed actin stress fibers." (PMID 23082182, 2012). "Infection of C. elegans with M. nematophilum provides a starting point for genetic screens to identify the molecular mechanisms by which RhoA and Ras act together to activate Raf." (PMID 22359503, 2012). "Prominent members are the GTP-binding proteins RhoA, Cdc42 and Rac1, which act as guanine nucleotide-regulated switches to induce various responses during the infection process." (PMID 22204307, 2011). "In contrast, dominant negative RhoA (N19) based lentiviral infection suppressed the expression of phorsphorylated JNK and cJun." (PMID 21949871, 2011). "Three days after empty lentivirus, RhoA N19 and RhoA L63 infection, green fluorescence was detected in epithelial and dermal tissues by in vivo fluorescence imaging." (PMID 21949871, 2011). "In the present study, we investigated the effect of RhoA activation on activin B-stimulated wound closure in KM mice by using infection of the cells with dominant negative or constitutively active RhoA expression constructs." (PMID 21949871, 2011). "Taken together, our analysis reveals that F11-mediated inhibition of RhoA signalling acts to enhance the spread of infection not only in vitro but also in vivo." (PMID 20041165, 2009). "Given this we imaged viral spread in live cells during plaque formation to assess more directly how F11-mediated inhibition of RhoA signalling enhances the spread of infection." (PMID 20041165, 2009). "We also found that the ability of F11 to bind RhoA also enhances viral spread in vivo in an intranasal mouse model of infection." (PMID 20041165, 2009). "Quantitative western blot analysis of Rhotekin-pull-down assays on infected cell extracts confirmed that the level of GTP-bound RhoA is significantly higher in ΔF11L than WR infected cells at 8 hours post infection." (PMID 20041165, 2009). "Our observations in confluent cell monolayers in culture indicate that F11 and its abililty to bind RhoA to inhibit its downstream signalling enhances the cell-to-cell spread of infection." (PMID 20041165, 2009). "Pre-incubation of Swiss 3T3 cells with Y-27632 significantly reduced the proportion of microcolonies with filopodia at 15 min (30%) and more drastically at 30 min (50%) post infection, These phenotypes parallel those seen with dominant-negative and siRNA RhoA." (PMID 19046338, 2009). "Our results clearly establish that viral-mediated inibition of RhoA signalling can enhance the spread of infection not only in cell monolayers, but also in vivo." (PMID 20041165, 2009). "Notably, the decrease in RhoA expression was consistently more pronounced following interaction with EVs compared to direct infection with the parasite, suggesting a significant role for T. cruzi-derived EVs in modulating host cell signaling pathways." (PMID 40623042, 2025). "The RhoA/ROCK/MLC signaling pathway was activated during the early stage of MVC infection, therefore, we investigated whether RhoA/ROCK1 signaling pathway is involved in MVC infection and entry." (PMID 40142587, 2025).
infection (continued). "Importantly, while prior studies applied RhoA inhibitors before infection, our model treated cells post-infection (at 48 hpi), yet still observed significant antiviral effects, reinforcing the relevance of RhoA as a conserved target across Orthoflavivirus." (PMID 40821819, 2025). "Notably, an increase in GTP-bound (active) forms of RhoA, Rac1 and Cdc42 was observed in WT cells after 1 h of infection; however, such activation was largely prevented in Egr-1-knockout cells." (PMID 38233877, 2024). "Additionally, infection with L. amazonensis or L. braziliensis led to reduced RhoA and gelsolin expression in BMDM." (PMID 37576604, 2023). "Similarly, in human macrophages, infection with L. amazonensis, L. braziliensis or L. infantum resulted in reduced Rac1, Cdc42, and RhoA expression in a 3D environment compared to uninfected controls." (PMID 37576604, 2023). "In the present report, we utilized a proximity-dependent biotinylating enzyme (TurboID) to characterize the US28 interactome under latent and lytic infection modes and focused our study on exploring the role of RhoA and RhoGEFs as an important US28 signaling intermediary." (PMID 37782657, 2023). "In contrast, we also demonstrated that infection with L. infantum led to increased RhoA expression in human dendritic cells, which could favor cell migration." (PMID 37576604, 2023). "Recently, it has been reported that Calcium ion (Ca2+) is a crucial factor in influenza virus internalisation and successful infection, and it activates a signalling axis comprising RhoA, phospholipases, phosphatidylinositol 4-phosphate 5-kinase and Rho-kinases." (PMID 35654795, 2022). "To establish whether InaC regulates the activity of RhoA during infection, we made use of a C. trachomatis L2 mutant in which the InaC gene was inactivated using Targetron (InaC KO Chlamydia)." (PMID 34903051, 2021). "Next, we assessed whether both mutant forms of RhoA are differentially recruited during infection with InaC KO Chlamydia." (PMID 34903051, 2021). "Whether InaC regulates RhoA and how both GTPases are coordinated during infection to generate their specific scaffolds at the optimal time is unknown." (PMID 34903051, 2021). "Infection of fibroblasts induced IL-11 secretion, which increased after RhoA depletion and may play a role in host cell survival." (PMID 33824207, 2021). "Changes in microfilaments in the form of stress fiber formation were evidenced at the very early stage of infection and were possibly triggered because of viral tethering to the host cell surface integrins and subsequent Ras homolog family member A (RhoA) activation." (PMID 33818275, 2021). "To test this hypothesis, we first investigated the impact of RhoA depletion on the formation of PTM-MTs during infection." (PMID 34903051, 2021). "The presence of RhoA inhibits the formation of PTM-MT scaffolds during infection." (PMID 34903051, 2021). "In addition to its role in migration, RhoA has also been implicated in early steps of HCMV lytic infection, as well as immune signaling during late infection." (PMID 33824207, 2021). "We demonstrated preliminarily that meningitic E. coli induced the expression of ANGPTL4 through the activation of PPARβ/δ signaling pathway, and ANGPTL4 contributed to the infection-mediated BBB disruption via the ARHGAP5/RhoA/MYL5 signaling cascade, affecting the actin cytoskeleton." (PMID 31766605, 2019). "MeV-PP and MeV infection of A549-SLAMF1 cells was reduced by a DN variant (N19) of RhoA (another GTPase), although the latter was not significant." (PMID 28100610, 2017). "Interestingly, we found that EPEC and EHEC strains expressing EspM also express either EspT or EspW, suggesting that activation of RhoA and Rac1 need to be coordinated during infection." (PMID 28630074, 2017). "We found that ANDV infection or N protein expression in MECs constitutively activates RhoA." (PMID 27795403, 2016). "ANDV infection and N protein expression activate RhoA in MECs." (PMID 27795403, 2016).
infection (continued). "Wild-type RhoA or Rac1 overexpressed cells had almost the same infection rates by T. gondii as the mock-treated cells, while RhoA-N19 or Rac1-N17 transfected cells and RhoA, Rac1 or RhoA + Rac1 siRNA-treated cells showed significantly diminished infection rates compared to mock cells." (PMID 23721065, 2013). "Our analysis demonstrated that absence of YopE caused no or only a small increase in Rac1/RhoA activation and Yop translocation during infection of murine macrophages with Y. pseudotuberculosis YPIII with or without treatment with CNFY." (PMID 24244167, 2013). "In our research, we are not clear about the upstream cell signaling component of the Rho and Rac GTPases involved in T. gondii infection, but we have witnessed the activation of RhoA and Rac1 of host cells and the reorganization of the cytoskeleton for PV formation during the infection of T. gondii." (PMID 23721065, 2013). "RhoA activity increased in A549 cells in the presence of hypoxia upon infection with P. aeruginosa." (PMID 23418576, 2013). "Some effector proteins, in particular YopE, were shown to inhibit Yop delivery by inactivation of RhoA and Rac1 most likely as part of an intra-cellular control mechanism which measures and adapts the amount of protein translocated by Yersinia during infection." (PMID 24244167, 2013). "We show that Gαq-RhoA signaling is a late step in the response to infection and their site of action defines the cellular targets of signals generated internally in response to infection." (PMID 22359503, 2012). "On the other hand, infection with recombinant adenovirus containing constitutively activated human RhoA (RhoA L63) led to increased RhoA activation and ROCK phosphorylation, as well as rearrangement of F-actin in HMVECs and increased permeability of HMVEC monolayers." (PMID 22251897, 2012). "Interestingly, lentiviral infection with constitutively active RhoA (L63) remarkably enhanced wound healing induced by activin B, while the dominant negative RhoA (N19) infection delayed wound closure." (PMID 21949871, 2011). "Moreover, the level of GTP-bound RhoA in F11-VK infected cells is similar to that observed during ΔF11L infections." (PMID 20041165, 2009). "Similar result was obtained after infection of 3T3 cells treated with RhoA siRNA." (PMID 19046338, 2009). "In order to determine if RhoA is involved in filopodia formation or stabilization, 3T3 Swiss cells were transfected with dominant-negative RhoAT19N and filopodia was enumerated at 15 and 30 min post infection with E2348/69Δmap overexpressing MapEPEC." (PMID 19046338, 2009). "F11-mediated inhibition of RhoA signalling is also responsible for stimulating virus-induced cell migration, which may also help to enhance the spread of infection." (PMID 20041165, 2009). "Interestingly, while the role of RhoA in infection-induced macrophage remodeling remains unclear, LPS specifically activates RhoA in bone marrow-derived macrophages (BMDMs)." (PMID 40721684, 2025). "Moreover, we further identified that RhoA/ROCK1 inhibitors effectively block MVC infection." (PMID 40142587, 2025). "In addition, we infected control (vector) and RhoA-overexpressing cells with PRV-GFP and fluorescent microscopy and flow cytometry assay showed that GFP positive cells were fewer in RhoA-overexpressing cells than in control cells, suggesting that RhoA overexpression inhibited PRV-GFP infection." (PMID 37968757, 2023). "In conclusion, Nef and Env likely inhibit RhoA in productively infected cells to neutralize its negative effects on outbound virus release, whereas soluble Tat and inbound Env might activate RhoA in uninfected cells to increase their permissibility to infection." (PMID 29401736, 2018). "Therefore the function of the SifA C-term in the mouse model of infection is probably not linked to function of RhoA-SseJ in virulence." (PMID 26268777, 2015).
infection (continued). "Indeed, an identical phenotype (i.e. rapid filopodia withdrawal with increased proportion of pedestals) was seen after infection of 3T3 cells with EPEC expressing MapΔTRL or infection of 3T3 cells transfected with dominant-negative RhoA or ezrin with E2348/69 Δmap overexpressing MapEPEC." (PMID 19046338, 2009). "Our data demonstrated that in the early stage of MVC infection, MVC induced the activation of RhoA and ROCK1 as well as the early activation of pMLC2, and the peak activation was observed at 15 min post-infection, followed by a gradual decline." (PMID 40142587, 2025). "This pro-invasive function contrasts with RHOA’s pathogen-specific roles in porcine viruses: it promotes endocytosis and tight junction disruption during CSFV/PSaV infection but inhibits PRV replication via cytoskeletal remodeling." (PMID 40999528, 2025). "(i) The WRD cells were pretreated for 1 h with specific inhibitors targeting RhoA (CCG-1423) or ROCK1 (Y27632), followed by MVC infection for 6 h, 12 h, and 18 h." (PMID 40142587, 2025). "A notable example is the infection of CD4+ T lymphocytes by HIV, where the activation of Rac1, Cdc42, and RhoA depends on the membrane localization of the viral protein Gag and its interaction with specific membrane phospholipids." (PMID 40316910, 2025). "Given that the activation of the RhoA/ROCK1/MLC2 signaling pathway mediates TJ disassembly, we observed that this process occurs during the early stage of MVC infection." (PMID 40142587, 2025). "Studies have demonstrated that ISKNV significantly upregulates mRNA transcription and protein expression of RhoA and ROCK following host cell infection." (PMID 40316910, 2025). "To understand the correlation between the RhoA/ROCK1/MLC2/Occludin pathway and MVC infection, we analyzed the protein expression levels of Occludin in WRD cells infected with MVC and evaluated the effects of RhoA and ROCK1 inhibitors on its expression." (PMID 40142587, 2025). "Activation of RhoA and Rac1, for example, modulates ACE2 expression, potentially increasing infection rates." (PMID 39653747, 2024). "Classical swine fever virus activated RhoA/ROCK and Rac1/Cdc42/PAK pathways in the early stage of infection, which helped virus entry into host cells by regulating the dynamic changes of the F-actin." (PMID 37968757, 2023). "Specifically, for flaviviruses, Japanese encephalitis virus (JEV) infection in neuronal cells rapidly activates RhoA and blocking RhoA reduces JEV entry and infection." (PMID 35215978, 2022). "Inhibition of the RhoA/ROCK/MLC pathway restores the gate and fence functions of TJs disrupted by PSaV infection." (PMID 33692204, 2021). "This concept is supported by the fact that each GTPase is activated at specific times during infection: 16 hpi for ARF1 and 32 hpi for RhoA." (PMID 34903051, 2021). "As expected, RVA induced the activation of pMLC, RhoA, and ROCK signaling molecules at early times of infection, peaking at 60 mpi." (PMID 33692204, 2021). "This induction of MLC expression by HCMV is not driven by miR-US25-1, since increased total MLC levels were also observed with infection with ΔmiR-US25-1 and ΔmiR-US25-1/RhoA shRNA viruses." (PMID 33824207, 2021). "Although WT HCMV-infected cells demonstrated decreased RhoA expression compared to mock-infected cells, ΔmiR-US25-1 infection resulted in increased RhoA expression compared to WT HCMV-infected fibroblasts and expression similar to that of mock-infected cells." (PMID 33824207, 2021). "We next examined RhoA-GTP levels in Aim2–/–, Asc–/– and Casp1–/– BMDMs during HSV1 and F. novicida infections." (PMID 34471287, 2021). "Transcription factors selected as biomarkers for targeting should be predicted for genes such as TLR7, TLR9, RHOA, IRF1, and IL6 since they are activated early in infection." (PMID 32872640, 2020). "We previously found that RhoA is inactivated by the GAP activity of myosin-9A, in an F11-dependent manner in late stages of infection." (PMID 28486133, 2017).
infection (continued). "TSCs normally restrict RhoA-induced MEC permeability, and we found that ANDV infection or N protein expression constitutively activated RhoA." (PMID 27795403, 2016). "Taken together, these experiments clearly demonstrate that RhoA/ROCK1 signaling plays an important role in the processes of autophagy and apoptosis that occur in the early and late stages of ARV S1133 infection of cultured Vero cells." (PMID 25944062, 2015). "Infection with a VopS positive but MAM deleted strain, leads to intermediate RhoA activation, presumably reflecting the cell's endogenous level of active RhoA." (PMID 26156628, 2015). "Taken together, these experiments clearly demonstrate that RhoA/ROCK1 signaling plays an important role in the processes of autophagy and apoptosis that occur in the early and late stages of ARV S1133-infection of Vero cells." (PMID 25944062, 2015). "At different time points following HeLa cell infection with S. meliloti, lysates were prepared and the amount of active, GTP-bound, Cdc42, Rac1 and RhoA precipitated with the GST-CRIB fusion protein was determined by western blotting." (PMID 23409119, 2013). "Echo30 infection leads to enhanced TRIO protein level, resulting in RhoA and RhoA targeted signaling activation, and contributing to SK-N-SH cell death." (PMID 22586486, 2012). "Echo30 infection activates TRIO-guanine nucleotide exchange factor (GEF) domains (GEFD2) and RhoA signaling in turn." (PMID 22586486, 2012). "RhoA depletion markedly diminishes ROCK activity and vimentin Ser72 phosphorylation, supporting the existence of a hierarchical RhoA/ROCK-vimentin signaling axis during infection." (PMID 41516263, 2025). "Considering that both ZIKV and DENV-4 manipulate cytoskeletal dynamics during infection, we evaluated whether MEL modulates RhoA activation." (PMID 40821819, 2025). "To test whether inhibition of RhoGTPases could affect HIV infection in U937 control or Myo9b-silenced cells, we treated these U937 with inhibitors to RhoA, B and C (C3) or to Rac1 (NSC23766) for 4 h before infection with VSV-G-pseudotyped HIV-1." (PMID 40167026, 2025). "Additionally, RhoA and ROCK inhibitors significantly reduced pMLC2 activation during early MVC infection, preventing TJ dissociation and partially restoring Occludin localization." (PMID 40142587, 2025). "In the case of JEV infection, it has been shown that entry is independent of clathrin, while the regulatory proteins of actin filaments, such as RHOA, RAC1, proteins of the ARP2/3 complex, and the N-WASP family (LIMK1, PAK1, and ROCK2), are crucial for the establishment of infection." (PMID 40733526, 2025). "Interestingly, levels of PKC and Rho-kinase remain unchanged during infection, contrasting with CSFV, which relies heavily on the RhoA/ROCK pathway for vimentin rearrangement." (PMID 41516263, 2025). "However, during lytic infection, US28-mediated RhoA signaling facilitates smooth muscle cell migration in response to RANTES." (PMID 37782657, 2023). "To determine whether RhoA participates in the regulation of Pol-III-directed transcription mediated by EGR1, we generated 293T and HepG2 cell lines stably expressing both EGR1 shRNA and RhoA–EGFP, using a lentiviral infection system." (PMID 35563324, 2022). "While RhoA-GTP was absent in WT BMDMs upon infection, it was present in Aim2–/–, Asc–/– and Casp1–/– BMDMs." (PMID 34471287, 2021). "In contrast, the Clostridium botulinum toxin C3, a pan-RhoA, B, and C inhibitor, blocked virus-induced cell contraction but not infection." (PMID 28486133, 2017). "Thus, even though VopS acts as a potent and irreversible inhibitor of RhoA, its rapid translocation and action on host cells requires MAM-mediated enhancement of RhoA activation early during infection." (PMID 26156628, 2015). "Likewise, the Trefoil Factor Initiated Mucosal Healing pathways were significantly suppressed in early stage of infection, more specifically, PTK2, GHR, RHOA, CTNNB1, MAPK3, and SHC1 genes." (PMID 24349118, 2013).